BNIP3 (BCL2 interacting protein 3)
Diseases named in the same sentence as BNIP3 in open-access papers (continued):
Sharing a sentence is not in itself a finding about the gene and the disease.
ischemic stroke (6 papers, 2020 to 2024). A stroke disorder caused by obstruction of blood flow to the brain, due to thrombotic (local blood clot formation) or embolic (due to a blood clot or other material traveling from another site) event. "BNIP3 inhibition appears to be a complementary approach to improve the efficacy of preconditioning for ischemic stroke." (PMID 36551300, 2022). "Based on the previous searches and reports, it was hypothesized that the significant protective effects of GP17 against ischemic stroke might be exerted via autophagy via Hif-1α/BNIP3 pathway or NAMPT-mediated pathway, namely SIRT1/2/3." (PMID 36572901, 2022). "It’s conceivable that BNIP3 inhibition could be a complementary approach to improve the efficacy of preconditioning for ischemic stroke." (PMID 36551300, 2022). "Notably, BNIP3-mediated mitophagy is shown to promote neuronal death both in vitro and in vivo upon ischemic stroke." (PMID 33537304, 2020). "When ischemic stroke occurs, hypoxic conditions activate HIF-1α, leading to upregulated expression of NIX and BNIP3 in cells, and thus activating the mitophagic pathway." (PMID 38650626, 2024). "In conclusion, our results indicated that TENS alleviated brain damage following ischemic stroke via inhibiting neuronal oxidative stress and pyroptosis and activating mitophagy, possibly via the regulation of TXNIP, BRCC3/NLRP3, and HIF-1α/BNIP3 pathways." (PMID 37101593, 2023). "Therefore, we hypothesize that HIF-1α plays a protective role by regulating BNIP3-mediated mitophagy, and TENS might regulate mitophagy through HIF-1α/BNIP3 pathway in ischemic stroke." (PMID 37101593, 2023). "Although BNIP3 and NIX/BNIP3L share high degree of sequence homology, elevated NIX/BNIP3L levels could not compensate BNIP3 depletion to trigger mitophagy and cell death in response to ischemic stroke." (PMID 33537304, 2020). "But its neuroprotective role in regulating autophagy has not been investigated in the context of ischemic stroke, and it is unclear whether GP17 and active saponin of Panax Notoginseng stems regulate autophagy via Hif-1α/BNIP3 pathway." (PMID 36572901, 2022).
leukemia (6 papers, 2005 to 2022). A malignant (clonal) hematologic disorder, involving hematopoietic stem cells and characterized by the presence of primitive or atypical myeloid or lymphoid cells in the bone marrow and the blood. "In line with the BV173 results, PDX engrafted female NSG mice developed aggressive leukemia associated with reduced heart size and weight, reduced cardiomyocyte CSA, impaired LV function, increased amount of TUNEL+ cardiac cells and cardiac BNIP3 expression." (PMID 35205731, 2022). "In line with several reports that BNIP3 is epigenetically silenced in leukemia and diverse solid tumors, BNIP3 expression could not be detected in leukemic BV173 cells." (PMID 35205731, 2022). "Finally, we determined the extent to which BNIP3 is methylated in primary tumours by examining the methylation status of BNIP3 in a panel of primary leukaemia specimens." (PMID 15756280, 2005).
multiple myeloma (6 papers, 2005 to 2024). "Among primary tumours, methylation of BNIP3 was detected in five of 34 (15%) acute lymphocytic leukaemias, six of 35 (17%) acute myelogenous leukaemias and three of 14 (21%) multiple myelomas." (PMID 15756280, 2005). "Methylation of the region around the BNIP3 transcription start site was detected in four acute lymphocytic leukaemia, one multiple myeloma and one Burkitt lymphoma cell lines, and was closely associated with silencing the gene." (PMID 15756280, 2005). "In the current study, however, we have shown for the first time that aberrant methylation of BNIP3 and histone deacetylation are involved in silencing the gene in a subset of ALLs, AMLs and multiple myelomas." (PMID 15756280, 2005). "Noticeably, human myeloma often associates up-regulation of MCL1 and silencing of BNIP3." (PMID 36358756, 2022). "Small interfering RNA for three up-regulated genes (BNIP3, IER3, and SEPW1) affected critical multiple myeloma endothelial cell functions mediating the cell overangiogenic phenotype, that is proliferation, apoptosis, adhesion, and capillary tube formation." (PMID 27713297, 2010). "Using COBRA, methylation of BNIP3 was detected in five of 34 (15%) ALL specimens, in six of 35 (17%) AML specimens and in three of 14 (21%) multiple myeloma specimens." (PMID 15756280, 2005). "Validation was focused on DIRAS3, SERPINF1, SRPX, BNIP3, IER3, and SEPW1 genes, which were not previously found to be functionally correlated to the overangiogenic phenotype of multiple myeloma endothelial cells." (PMID 27713297, 2010).
clear cell renal cell carcinoma (5 papers, 2022 to 2025). "PSME2 overexpression has been linked to clear cell renal cell carcinoma invasion by blocking BNIP3-mediated autophagy." (PMID 35656090, 2022). "According to previous studies, PSME2 plays the role of promoting tumor progression in clear cell renal cell carcinoma, which is positively correlated with the ability of invasion regulating BNIP3-mediated autophagy." (PMID 36583022, 2022). "Interestingly, the cancer type with the highest BNIP3 expression is clear cell renal cell carcinoma (ccRCC)." (PMID 35912211, 2022).
esophageal cancer (5 papers, 2014 to 2020). A primary or metastatic malignant neoplasm involving the esophagus. "The increased expression of BNIP3 and Beclin initiated autophagy at an early stage, which was mediated by microtubule-associated protein 1 light chain 3 (LC3) in KYSE 170 cells after treatment with EDHB for 12 h, ultimately result in the apoptosis of esophageal cancer cells." (PMID 25232961, 2014). "AKR1C1/C2 facilitated the induction of early autophagy and late apoptosis by BNIP3 and NDRG1 in ESCC cells after EDHB treatment, thereby promoting the EDHB-induced inhibition of esophageal cancer cell proliferation." (PMID 26934124, 2016). "Previous research has also shown that EDHB inhibits esophageal cancer cell proliferation by increasing autophagy and apoptosis through NDRG1 and BNIP3 and markedly increases AKR1C1, AKR1C2, and AKR1C3 mRNA expression." (PMID 26934124, 2016). "In summary, our observations indicated that AKR1C1/C2 promoted the inhibition of cell proliferation through either EDHB metabolism or BNIP3 and NDRG1 expression and induced early autophagy and late apoptosis in esophageal cancer cells." (PMID 26934124, 2016). "Interestingly, we found that EDHB treatment not only led to apoptosis but also autophagic cell death via the up-regulation of BCL-2/EIB-19K-interacting protein 3 (BNIP3) and Beclin and the down-regulation of BCL-2 in the esophageal cancer KYSE 170 cells." (PMID 25232961, 2014). "The increased expression of BNIP3 and Beclin initiated autophagy at an early stage, which was mediated by LC3 in KYSE 170 cells after treatment with EDHB for 12 h, ultimately resulting in the apoptosis of esophageal cancer cells." (PMID 25232961, 2014).
Insulin resistance (5 papers, 2018 to 2024). Increased resistance towards insulin, that is, diminished effectiveness of insulin in reducing blood glucose levels. "Briefly, both BNIP3 and SLC27A1 have been strongly associated with insulin resistance phenotypes." (PMID 33362275, 2020). "Protein expression for Mfn1 (P < 0.001), PGC1α (P < 0.05), BNIP3 (P < 0.0001), and mitochondrial complexes I‐V (P < 0.01) was also increased by RYGB, and Mfn1 expression negatively correlated with body weight, insulin resistance, and fasting plasma insulin." (PMID 29464885, 2018).
invasive carcinoma (5 papers, 2016 to 2024). A carcinoma that is not confined to the epithelium, and has spread to the surrounding stroma. "Other studies made a distinction between ductal carcinoma in situ (DCIS) and invasive carcinoma, suggesting that BNIP3 upregulation was correlated with higher risk of relapse and shorter disease-free survival only in DCIS." (PMID 35912211, 2022). "The nuclear expression of BNIP3 in invasive carcinomas was significantly correlated with decreased tumor size, low tumor grade, and estrogen receptor positivity." (PMID 39472438, 2024). "Meanwhile, up-regulated expression of BNIP3 has been revealed in ductal carcinoma in situ and invasive carcinoma, which suggested a regulatory role of BNIP3 in BC progression." (PMID 35200106, 2022). "In DCIS, the expression of BNIP3 and Nix are increased, while BNIP3 is not expressed in invasive carcinoma, which is related to tumor cell proliferation index and lymph node metastasis." (PMID 32587855, 2020).
Obesity (5 papers, 2014 to 2026). Accumulation of substantial excess body fat. "Obesity caused an activation of all the autophagy-related genes in WT animals while only Bnip3 and Cat L were induced in Hp-/- mice." (PMID 24959824, 2014). "Collectively, these results showed that Pink1/Parkin signaling, but not Fundc1 or Bnip3/Nix, was crucial for enhanced mitophagy in the heart or H9c2 cells in metabolic disorders during obesity." (PMID 34050133, 2021).
viral infection (5 papers, 2011 to 2025). "SRBSDV P7-1 interacts with the mitophagy receptor BNIP3 (BCL2 interacting protein 3) and induces BNIP3-mediated mitophagy by bridging autophagosomes and mitochondria for maintaining persistent viral infection in insect vectors." (PMID 36298813, 2022). "Whether BNIP3 and TMEM74 are effective during viral infection is unknown, although they might both (co)-regulate cellular responses to viral infection through autophagy induction." (PMID 22174682, 2011). "Expression of CXADR, BNIP3, or SPARCL1 was not downregulated by the ETV6/RUNX1 fusion in the absence of a viral infection (data not shown)." (PMID 41497616, 2025).
asthma (4 papers, 2016 to 2025). "We applied the LASSO logistic regression algorithm on the basis of DEGs and differentially expressed PRGs between C1 and C2 subtypes to identify the BNIP3 gene as a pyroptosis-related diagnostic marker for asthma." (PMID 35967302, 2022). "The mitophagy mediated by BNIP3 can promote the proliferation and migration of ASMCs and directly participate in the pathological process of airway remodeling in asthma." (PMID 41026942, 2025). "For instance, FUN14 domain-containing protein 1 (FUNDC1) dominates hypoxia-induced mitophagy in pulmonary fibrosis (PF), whereas BCL2/Adenovirus E1B 19 kDa protein-interacting protein 3 (BNIP3) is pivotal in asthma-related airway remodeling." (PMID 41026942, 2025). "Animal experiments confirmed that the content of BNIP3 protein in the lung tissue of the asthma mouse model is significantly downregulated and the BNIP3 mRNA shows the same trend (P<0.01) compared with those of normal mice." (PMID 35967302, 2022). "The noncoding RNA regulatory mechanism of BNIP3 was subsequently explored, and 64 miRNAs were predicted from three databases, of which four miRNAs presented functions in asthma." (PMID 35967302, 2022). "Note that the expression of BNIP3 was upregulated in properly controlled asthma subtypes but positively correlated with typical type-2 inflammatory cells, such as M2 macrophages, in subsequent immune infiltration analyses." (PMID 35967302, 2022). "Samples were divided into two groups with high- and low-BNIP3 expression levels for single-gene GSEA analysis to explore the role of BNIP3 in asthma." (PMID 35967302, 2022). "In addition to the classical pathway, the autophagy receptor BNIP3 is specifically up-regulated in specific cell types: the expression of BNIP3 in airway smooth muscle cells (ASMCs) of asthma patients is significantly increased." (PMID 41026942, 2025). "BNIP3 expression is upregulated in the airway smooth muscle cells of patients with asthma." (PMID 35747690, 2022). "Consistent with the PCR array data, the transcriptional expression of Bcl-2, an anti-apoptosis factor, was markedly decreased in the testis of asthma mice, while the mRNA transcription of pro-apoptosis genes including Bax, BNIP3, caspase-9 and AIF were enhanced significantly in asthmatic testis." (PMID 26938720, 2016). "DNA ladder and immunochemistry showed significant increase in apoptotic index of the asthmatic testis, whereas a decrease in mRNA expression of Bcl-2 and increases in Bax, BNIP3, caspase-9, and AIF were observed in the asthma group." (PMID 26938720, 2016). "Although mitophagy-related proteins such as PINK1, BNIP3, and FUNDC1 typically exhibit compensatory up-regulation in various pathologies, their expression is significantly reduced in nasal polyp tissues of asthma patients with chronic rhinosinusitis with nasal polyps (CRSwNP)." (PMID 41026942, 2025).
Cachexia (4 papers, 2019 to 2024). Severe weight loss, wasting of muscle, loss of appetite, and general debility related to a chronic disease. "The expression levels of mitophagy-related proteins, such as microtubule-associated protein 1 light chain 3 beta (MAP1LC3β), Parkin, PTEN induced kinase 1 (PINK1), and BCL2 interacting protein 3 (BNIP3), are altered in cachexia." (PMID 36361713, 2022). "Quantitative reverse-transcriptase PCR (qRT-PCR) of cardiac muscle demonstrated that R848 decreased expression of Mafbx and Murf1, and autophagy-associated transcripts frequently upregulated in cardiac tissue during cachexia (Bnip3, Ctsl, Gabarapl)." (PMID 31615993, 2019). "In the current study, BNIP3 knockdown was performed acutely, locally and using a model producing severe cachexia, as opposed to chronic and whole-body BNIP3 loss in mice bearing tumors that produce mild wasting." (PMID 39766033, 2024). "Markers of autophagy such as Bnip3 are consistently upregulated in experimental cachexia; however, whether or not upregulation of the ALS is beneficial or detrimental in cachexia is unknown." (PMID 36072367, 2022).
cholangiocarcinoma (4 papers, 2022 to 2025). A carcinoma that arises from the intrahepatic biliary tree (intrahepatic cholangiocarcinoma) or from the junction, or adjacent to the junction, of the right and left hepatic ducts (hilar cholangiocarcinoma). "Similar to our results, a previous study also emphasized the promoting role of hypoxia-associated autophagy caused by up-regulated BNIP3 on cell metastasis in cholangiocarcinoma." (PMID 35200106, 2022). "BNIP3 has also been applied in a RiskScore model of cholangiocarcinoma, expressing significantly lower in cholangiocarcinoma than normal tissues but higher expression is related to poorer prognosis, as in BC." (PMID 40337509, 2025). "Encouragingly, a Genome-wide association studies (GWAS) and experimental studies also identified BNIP3 as a key gene involved in the process of cholangiocarcinoma-to-sarcoma transdifferentiation." (PMID 40438322, 2025). "In another study on ferroptosis in cholangiocarcinoma BNIP3 was identified as a key gene involved in ferroptosis and was used to construct a prognostic risk model for cholangiocarcinoma patients." (PMID 40438322, 2025). "The survival analysis was performed with all cancer types in the TCGA project, suggesting BNIP3 mRNA expression as a worse prognostic factor also for cervical squamous cell carcinoma and endocervical adenocarcinoma (CESC), cholangiocarcinoma (CHOL), and sarcoma (SARC)." (PMID 35912211, 2022).
ductal carcinoma in situ (4 papers, 2009 to 2022). "However, in breast ductal carcinoma in situ, nuclear BNIP3 was associated with a 3‐fold increased risk of recurrence and shorter disease‐free survival." (PMID 36200262, 2022). "BNIP3 mRNA was also strongly expressed in ductal carcinoma in situ (DCIS) and correlated with a high grade phenotype and presence of invasive disease." (PMID 19505343, 2009).
infarction (4 papers, 2007 to 2017). A localised pathological necrosis of tissue resulting from obstruction of the blood supply usually by a thrombus, an embolus, or vascular torsion. "A recent study demonstrated that BNIP3-deficient mice exhibited diminished cardiac dilatation and preserved ventricular systolic performance post-infarction." (PMID 28340591, 2017). "Finally, high levels of PAI-1 have been found to be associated with cardiovascular disease, and BNIP3 has been found to be a mediator of myocardial death after infarction, again allowing one to surmise that the induction of these two HIF target genes could affect endothelial dysfunction." (PMID 17233898, 2007).
non-alcoholic fatty liver disease (4 papers, 2020 to 2024). "SIRT3 activates ERK-CREB signaling to promote BNIP3 activity, thus inducing BNIP3 regulated mitotic resistance to nonalcoholic fatty liver disease." (PMID 32724473, 2020). "Further, it could also activate mitophagy through an enhancement in BNIP3 expression, ameliorating non-alcoholic fatty liver disease." (PMID 37998340, 2023). "Furthermore, for non-alcoholic fatty liver disease, SIRT3 overexpression can protect liver cells by promoting BNIP3-mediated-mitophagy and reducing mitochondrial apoptosis, thus effectively treating non-alcoholic cirrhosis." (PMID 34912814, 2021).
osteoarthritis (4 papers, 2020 to 2024). A noninflammatory degenerative joint disease occurring chiefly in older persons, characterized by degeneration of the articular cartilage, hypertrophy of bone at the margins and changes in the synovial membrane. "Since Cpt1b is localized in the outer mitochondrial membrane, we next wanted to investigate the expression and potential role of Bnip3 in the muscle pathophysiology of osteoarthritis and osteoporosis." (PMID 39456222, 2024). "To clarify the expression of BNIP3 during the occurrence and development of osteoarthritis, we used the LPS to stimulate the ATDC5 cells and determined the levels of BNIP3 in these cells." (PMID 32723351, 2020). "In this study, we establish the overexpression BNIP3 chondrocytes and use the lipopolysaccharide (LPS) to stimulate these cells to simulate the physiological environment of osteoarthritis." (PMID 32723351, 2020). "For further research on the effect of BNIP3 on the development of osteoarthritis, we used the lentivirus to establish the overexpression BNIP3 ATDC5 cells." (PMID 32723351, 2020). "Trehalose administration restored disrupted autophagic flux and mitophagy by activating Bnip3 and increasing the co-localization of Bnip3 with mitochondria in a mouse osteoarthritis model." (PMID 32679664, 2020).
preeclampsia (4 papers, 2021 to 2025). Preeclampsia is a hypertensive disorder of pregnancy that is characterized by new-onset hypertension with proteinuria presenting after 20 weeks of gestation, and depending on mild or severe forms may initially present with severe headache, visual disturbances, and hyperreflexia. "Our previous research has demonstrated that excessive BNIP3-mediated mitophagy can induce apoptosis of trophoblasts in the placenta in cases of preeclampsia (PE)." (PMID 40242759, 2025). "Our findings indicate that HIF-1α and BNIP3, as well as its mediated mitophagy, are upregulated in the placentas of pregnant women with preeclampsia (PE), as well as in a PE-like mouse model." (PMID 40242759, 2025). "The study further elucidates the role of BNIP3 in inflammation in preeclampsia (PE) and proposes that BNIP3 could potentially serve as a target for the treatment of pregnancy-related diseases manifesting as placental inflammation, such as PE." (PMID 40242759, 2025). "In this review, we compiled current studies investigating the role of BNIP3, DRAM1, and FUNDC1, mediators of receptor-mediated mitophagy, in the progression of preeclampsia and the role of mitophagy pathways in the pathophysiology of low birth weight." (PMID 36289801, 2022).